BRCA1 (BRCA1 DNA repair associated)
Diseases named in the same sentence as BRCA1 in open-access papers (continued):
Sharing a sentence is not in itself a finding about the gene and the disease.
breast cancer (continued). "To analyze syntenic genomic regions for overlapping CNAs, we applied two statistical frameworks to BRCA1-deficient, BRCA2-deficient and BRCA1/2-proficient control mouse and human breast cancers: a total of six tumor groups." (PMID 20735817, 2010). "This question is perhaps more relevant because sporadic cases of breast cancer are far more common than hereditary cases; in fact, hereditary breast cancer are consider to represent 5 to 10 %, and mutation of BRCA1 1 to 2%, of all cases." (PMID 21321378, 2010). "For a random 30-year-old breast cancer patient, the BRCA1 mutation carrier probability is approximately 10 times greater for a patient with ER-CK14+CK5/6+ versus ER-CK- breast tumour." (PMID 20482762, 2010). "In breast cancers from individuals with inherited BRCA1 mutations one finds more frequent losses on 4p, 4q, 5q, Xp and Xq and gains of 10p and 16q compared to breast tumors from individuals without BRCA1 mutations." (PMID 20885788, 2010). "Between 25-40% of these cases involves the inheritance of one defective copy of either the BRCA1 gene or the BRCA2 gene which predisposes women in these families to a ~50-80% lifetime risk of developing breast cancer and to a lesser extent ovarian cancer." (PMID 20735817, 2010). "Approximately 3% to 5% of all breast cancers and approximately 10% of ovarian cancers are due to inherited mutations in the breast and ovarian cancer susceptibility 1 or 2 genes (BRCA1 or BRCA2)." (PMID 20920338, 2010). "Methylation of the BRCA1 promoter, which leads to a reduced expression of BRCA1, has been reported to be present in 11 to 14% of sporadic breast cancers, where it is associated with a higher histological grade and a triple-negative phenotype." (PMID 20979652, 2010). "The results of this large analysis show that patients considered at H risk of being BRCA1 carriers had a better OS than patients considered at IS increased risk or to have sporadic breast cancer." (PMID 20219108, 2010). "In early-onset breast cancer, pathogenic mutations in BRCA1 were found in 4 cases of 64 patients analyzed (6.3%)." (PMID 20380699, 2010). "Using this combinatorial approach we were able to demonstrate a threefold enrichment of genes that contain SNPs associated with breast cancer risk for BRCA1 or BRCA2 mutation carriers." (PMID 21114847, 2010). "Next, we identified which of these CNAs occur both in mouse BRCA1- or BRCA2-deficient mammary tumors and in human BRCA1- or BRCA2-mutated tumors." (PMID 20735817, 2010). "Using either CD44+/CD24- or CD133+ cells isolated from Brca1-deficient mouse mammary tumors, expression of Sox1 was found to be significantly higher in these cells when compared to their counterparts." (PMID 20929579, 2010). "LVI is frequent in BRCA1 germline mutation related breast cancers, but seems to occur as often in sporadic controls matched for age, grade and tumor type." (PMID 20398395, 2010). "The mean age at diagnosis was 45.2 years for the 24 ER+ first breast cancers with loss of wt BRCA1, compared to 50.1 years in those 8 ER+ first cancers that retained a wt BRCA1 allele." (PMID 21080930, 2010). "By collecting all the information about individuals affected by breast cancer, very long-term survivors can be identified by predicting a predisposition for being a BRCA1-mutation carrier in the descendants." (PMID 20219108, 2010). "We estimate that 32% of breast cancer FRR for ER-negative disease is explained by BRCA1 and BRCA2 mutations alone." (PMID 20146796, 2010).
breast cancer (continued). "More specifically, the activation of AKT1 shows a deficient phenotype in BRCA1 and HR, revealing molecular similarities between hereditary and sporadic breast cancers." (PMID 21321378, 2010). "The frequency of breast cancer in BRCA1 founder mutation carriers was 20%; 95% CI = 5.7 - 51.0] but in tested mutation-negative probands - 10.6% (95% CI = 8.3 - 13.3%)." (PMID 21034437, 2010). "The group therefore subsequently concludes that BPM reduces the risk of breast cancer in women with BRCA1/2 mutations by approximately 90%." (PMID 20961453, 2010). "In Latvia, 26% of young breast cancer patients (diagnosed before age 48) were found to carry mutations in BRCA1." (PMID 20380699, 2010). "In breast carcinoma, the total number of genomic changes, as determined by cytogenetics, was found to be almost two times higher in tumors with BRCA1 mutation than in control group." (PMID 20843305, 2010). "It was reported that basal-like and BRCA1-associated breast carcinomas, which are also related were both enriched with CD44+/CD24− candidate stem cells, and BRCA1 has been suggested to represent a stem cell regulator." (PMID 20010944, 2010). "TOPBP1 encodes a protein that shares homology to BRCA1, is aberrantly expressed in breast carcinomas and has a critical role in DNA damage and replication checkpoint pathways." (PMID 21108795, 2010). "The major breast cancer (BC) predisposing genes, BRCA1 and BRCA2 were identified in 1994 and 1995, respectively." (PMID 20219108, 2010). "Three of 31 early onset (≤ 35 years) breast cancer cases had deleterious mutation, 2 in BRCA1 (7%) and 1 in BRCA2 (3%) gene." (PMID 19656415, 2009). "Despite recent advances in the development of GEM models of EOC and the existence of mouse models of Brca1-associated inherited breast cancer, analogous mouse models that develop Brca1-associated inherited invasive EOC have been more difficult to develop." (PMID 20046879, 2009). "In this study, we demonstrate that EZH2 expression is high in breast tumors from BRCA1-mutation carriers, similar to that observed in our mouse model for BRCA1-deficient breast cancer." (PMID 19709408, 2009). "Unclassified variants (UVs) in the BRCA1/BRCA2 genes are a frequent problem in counseling breast cancer and/or ovarian cancer families." (PMID 19200354, 2009). "Evaluation of BRCA1 protein expression in 1940 breast cancer cases has shown that about 50% of the tumors showed loss of nuclear expression or cytoplasmic localization of the protein." (PMID 19695104, 2009). "In contrast to the high proportion among BRCA1-associated breast cancer, only about 15% of all women with breast cancer have triple-negative cancers." (PMID 19298662, 2009). "Examples of currently used genetic biomarkers are the breast cancer susceptibility gene 1 (BRCA1) or breast cancer susceptibility gene 2 (BRCA2)." (PMID 19128481, 2009). "It is unlikely that this group of women is representative of all women from BRCA1/2 mutation-positive families or other healthy women in the general population who are at high risk of breast cancer." (PMID 19602282, 2009). "We have obtained DNA samples from a large group of breast cancer patients (nearly all Jewish Ashkenazi) for analysis of BRCA1/2 mutations and modifier genes." (PMID 19226467, 2009). "In conclusion, our results indicate that 2.6% of the Greek patients developing breast cancer independently of age or family history and 10% of Greek patients developing breast cancer before age 40 carry one of four common Greek BRCA1 mutations." (PMID 19491894, 2009). "For women with a significant family history of breast cancer, genetic testing for mutations in BRCA1 and BRCA2 is available throughout Canada and elsewhere." (PMID 19088722, 2009).
breast cancer (continued). "We also looked at the relationships between MRI and mammographic breast density measures and BRCA1/2 genetic status, and attempted to assess their relative usefulness for breast cancer risk prediction." (PMID 19903338, 2009). "Breast cancers of BRCA1 mutation carriers frequently show poor responses to neoadjuvant therapy with docetaxel, whereas platinum-based chemotherapy seems to be highly effective." (PMID 19904273, 2009). "Of the genes examined, only genetic variants in IGF1R and its adaptor protein IRS1 were associated with risk of breast cancer in BRCA1 carriers." (PMID 19843326, 2009). "The rationale for antihormonal therapy as an alternative for prophylactic surgery comes from the observation that oophorectomy prevents breast cancer in BRCA1 mutation carriers." (PMID 19904273, 2009). "The association between high density and risk is also believed to be present in women who are already at an elevated risk of breast cancer as a result of carrying a mutation in the BRCA1 or BRCA2 genes." (PMID 19903338, 2009). "Deleterious germline mutations of BRCA1 have been estimated to occur in 1 in 40 Ashkenazi Jews and 1 in 400 non-Ashkenazi and are responsible for a significant fraction of inherited breast cancer cases." (PMID 19695104, 2009). "We estimate the lifetime risk of breast cancer in these women to be approximately 40%, or roughly one-half of a BRCA1 or BRCA2 mutation carrier." (PMID 19088722, 2009). "Breast cancer is the most common cancer in women and has been associated with a number of specific genetic mutations, namely BRCA1/2, which accounts for approximately 5% of reported cases." (PMID 19830129, 2009). "In our analyses, Amp13q34 is a low frequent genomic event in overall breast cancer (around 4.5%) but the rate increases when analyzing BRCA1-associated breast cancer (8.1%) or basal-like tumors (about 20%)." (PMID 19995430, 2009). "Of the 111 breast cancer patients among our cohort that reported a family history of breast and/or ovarian cancer, 17 have been found to carry one of the four BRCA1 mutations (15.3%)." (PMID 19491894, 2009). "After comparing gene expression patterns of BRCA1-deficient mouse mammary tumors with BRCA1-proficient control tumors, we noted that Ezh2 expression was particularly high in BRCA1-deficient tumors." (PMID 19709408, 2009). "Our findings confirm the serious prognosis of BRCA1-associated breast cancer even when diagnosed at an early stage, and that type of treatment does not influence prognosis." (PMID 19366445, 2009). "In particular, the relationship between the breast cancer predisposing gene BRCA1 and XIST, the main mediator of X chromosome inactivation, has been intensely investigated, but still remains controversial." (PMID 19440381, 2009). "DNA from breast cancer patients was obtained for analysis of one of the three common BRCA1/2 mutations and MDM2 SNP309." (PMID 19226467, 2009). "Among BRCA1 carriers, significant associations were found between risk of breast cancer and LD blocks in IGF1R (global P = 0.011 for LD block 2 and global P = 0.012 for LD block 11)." (PMID 19843326, 2009). "The most recently developed conditional Brca1 mammary tumour models closely mimic several important aspects of human BRCA1-associated breast cancer and therefore serve as important tools for the development of novel therapies for this disease." (PMID 19904273, 2009). "There is therefore a strong rationale for why genetic variation in IGF1R and IRS1 would be important in breast cancer risk in BRCA1 carriers." (PMID 19843326, 2009). "The main conclusions in our study, are that BRCA1 associated breast cancer has a serious prognosis, and this is especially so for early stages." (PMID 19366445, 2009).
breast cancer (continued). "The p.R1699W BRCA1 variant has already been classified as deleterious in the Breast Cancer Information Core." (PMID 19200354, 2009). "Women with mutations in the breast cancer genes BRCA1 or BRCA2 have an increased lifetime risk of developing breast, ovarian and other BRCA-associated cancers." (PMID 21637503, 2009). "We assessed the relationships of the MRI and mammographic measures to one another, to standard anthropometric and hormonal factors, to BRCA1/2 genetic status, and to breast cancer risk (60 cases) using linear and Poisson regression." (PMID 19903338, 2009). "One hundred and sixty-seven women with disease-associated germline BRCA1 mutations and breast cancer from 1980 to 2001 were identified." (PMID 19366445, 2009). "Most of breast cancers are considered sporadic and modulation of the two major genes BRCA1 and BRCA2 expressions caused by tissue-specific somatic mutations lead to this pathology." (PMID 19442290, 2009). "We developed a mouse model mimicking human BRCA1-deficient breast cancer to gain insight into the molecular progression of BRCA1-deficient tumors and to test putative therapies." (PMID 19709408, 2009). "The average cumulative risk of breast cancer in a BRCA1 and BRCA2 mutation carrier is 65% and 45% by the age of 70 years, respectively." (PMID 19656415, 2009). "A number of studies suggest that breast cancers associated with BRCA1 mutations are likely to be triple-negative and the majority of these are also the basal phenotype." (PMID 19298662, 2009). "It has been estimated that the risk of developing breast cancer in those with BRCA1 or BRCA2 mutations is 45% to 65% respectively." (PMID 19144138, 2009). "There is some evidence to suggest that inherited mutations in breast cancer (BrCa) and ovarian cancer (OvCa) risk genes BRCA1 and BRCA2 also increase the risk of PCa." (PMID 19935797, 2009). "Cancer risk counseling of patients and families with an unclassified variant of the breast cancer (BC) genes BRCA1 and/or BRCA2 (MIM numbers 113705 and 600185, respectively) has become a prominent issue for genetic counselors and oncologists." (PMID 19200354, 2009). "In this study, we evaluated the effectiveness of a combination of selected eligibility criteria and IHC characteristics of breast cancer to identify patients who have a higher probability of being BRCA1 mutation carriers." (PMID 19818148, 2009). "Germline mutations in the BRCA1 or BRCA2 genes significantly increase the risk of developing early-onset breast cancer." (PMID 19589159, 2009). "Gene expression profiling revealed a strong resemblance between BRCA1-mutated tumours and sporadic basal-type breast cancer." (PMID 19904273, 2009). "I don't think that there's really strong evidence to support a reduction in breast cancer occurrence [in BRCA1 and BRCA2 mutation carriers]." (PMID 19409108, 2009). "MRI has been shown to be effective in detecting small breast cancers in BRCA1 and BRCA2 mutation carriers." (PMID 19088722, 2009). "BRCA1 mutation carriers have a lifetime risk of about 80% for developing breast cancer and a 40% lifetime risk for developing ovarian cancer." (PMID 19904273, 2009). "We evaluated the effectiveness of a combination of homogeneously selected criteria and immunohistochemical (IHC) characteristics of Familial Breast Cancers (FBCs) in detecting BRCA1 mutation carriers." (PMID 19818148, 2009). "We use the algorithm for breast cancer related to BRCA1 and BRCA2 mutations, but it can be easily applied to other cancers, provided the penetrance functions of the genes involved are known." (PMID 19563646, 2009). "We demonstrate by specific knock-down experiments that EZH2 overexpression is functionally relevant in BRCA1-deficient breast cancer cells." (PMID 19709408, 2009). "Although genetic testing for inherited BRCA1 mutations provides valuable information to women at high risk of breast cancer, carriers of BRCA1 mutations have few clinical options to reduce their cancer risk." (PMID 19904273, 2009).
breast cancer (continued). "There are several reports of DL-related pain in women at high risk of breast cancer, but few women who were known to be BRCA1/2 mutation carriers, and even fewer who were unaffected BRCA1/2 mutation carriers, were included in these reports." (PMID 19602282, 2009). "In our study 10/15 BRCA1 mutation positive cases were breast cancer and 2/16 were ovarian cancer cases." (PMID 19656415, 2009). "Although the results obtained with this conditional Brca1 mouse model hold promise for the development of anti-progesterones as prophylactic therapy for BRCA1-associated breast cancer, the jury is still out on this for several reasons." (PMID 19904273, 2009). "With regard to this time issue, conditional Brca1 mouse models that develop mammary tumours with strong resemblance to human BRCA1-mutated breast tumours can be very helpful in predicting response and resistance to conventional and targeted therapeutics." (PMID 19904273, 2009). "In this study, we investigate the association of variants in genes involved in IGF signaling and risk of breast cancer in women who carry deleterious BRCA1 and BRCA2 mutations." (PMID 19843326, 2009). "Vast majority of studies has shown a highly increased risk of developing breast cancer in BRCA1 or BRCA2 mutation carriers with also a greater incidence of a second contra-lateral tumour." (PMID 19232099, 2009). "Recapitulation of these characteristics in mouse models is crucial for preclinical development of chemoprevention strategies and tailored therapies for BRCA1-associated breast cancer." (PMID 19904273, 2009). "A hospital-based cohort of 987 unselected breast cancer cases was analysed to determine the frequency of the four most common mutations of the BRCA1 gene." (PMID 19491894, 2009). "BRCA1 is considered to be a breast tumor suppressor gene, and reduced expression or loss of function is associated with ER-negative basal-type breast cancers." (PMID 20049202, 2009). "We show that aromatase expression is significantly higher in BRCA1 mutation carriers, in patients who had experience breast cancer but also in women who had a high risk for breast cancer and had prophylactic removal of their breast tissue." (PMID 19445691, 2009). "In the past years, these mouse models have been further improved to recapitulate the salient features of human BRCA1-associated breast cancer, such as ‘triple-negative’ status, increased genomic instability and increased expression of basal epithelial markers." (PMID 19904273, 2009). "In a study of 254 white women from the UK, diagnosed with breast cancer before age 36, a germline BRCA1 or BRCA2 mutation was identified in only 6% (ref 16)." (PMID 19298662, 2009). "BRCA1-associated breast cancers differ from sporadic breast cancer with regard to prognostic markers." (PMID 19366445, 2009). "Prophylactic surgery is still one of the most important measures of breast cancer prevention for BRCA1 mutation carriers." (PMID 19904273, 2009). "Is the CD44+/CD24low/- phenotype associated with CSCs only in certain breast cancers, predominantly basal-like or BRCA1?" (PMID 19555472, 2009). "This approach was shown to link breast cancer susceptibility to centrosome dysfunction in tumours carrying BRCA1 mutations, and importantly identified the HMMR gene as a new breast cancer susceptibility gene." (PMID 19285540, 2009). "Germline mutations in BRCA1 or BRCA2 genes have been demonstrated to increase the risk of developing breast cancer." (PMID 19232099, 2009). "The CHEK2*1100delC mutation confers a low risk of breast cancer in non-BRCA1/BRCA2 mutation carriers." (PMID 19656415, 2009). "In cell lines from mammary tumors Brca1 knockout mice, the expression of CD133 cells is associated with stem cell properties as well as CD44+/CD24-/low phenotype." (PMID 19555472, 2009).